FRMD3 (FERM domain containing 3)
Description:
Putative tumor suppressor gene that may be implicated in the origin and progression of lung cancer.
Synonyms: 4.1O; EPB41L4O; MGC20553; EPB41LO; P410
Tractability: Antibody: UniProt predicts a signal peptide or a membrane-spanning region; the Human Protein Atlas places it where antibodies can reach. PROTAC: ubiquitination databases record sites on it.
Gene: Protein-coding gene on chromosome 9 (83,242,990 to 83,538,737, reverse strand). Ensembl gene ENSG00000172159.
Subcellular location: Membrane
Subcellular location (Human Protein Atlas): Golgi apparatus; Plasma membrane
Gene Ontology:
Molecular function: protein binding; cytoskeletal protein binding
Biological process: actomyosin structure organization
Cellular component: cytoskeleton; membrane
Genetic constraint (gnomAD): Loss-of-function variants: 16 observed, 43.19 expected, observed/expected ratio (o/e) 0.37, 90% interval 0.25 to 0.56. The upper end of that interval is the gene's LOEUF score, 0.56, which puts it in group 2 of 6, group 1 being the genes least tolerant of losing a copy. Missense variants: 513 observed, 602.42 expected, observed/expected ratio (o/e) 0.85, 90% interval 0.79 to 0.92. Synonymous variants: 231 observed, 229.63 expected, observed/expected ratio (o/e) 1.01, 90% interval 0.9 to 1.12.
Homologues: Orthologues: chimpanzee FRMD3 (99% identical), pig FRMD3 (97% identical), rabbit FRMD3 (93% identical), macaque FRMD3 (92% identical), mouse Frmd3 (91% identical), rat Frmd3 (91% identical), dog FRMD3 (90% identical), guinea pig FRMD3 (80% identical), tropical clawed frog frmd3 (75% identical), zebrafish frmd3 (49% identical), Caenorhabditis elegans frm-1 (29% identical), Drosophila melanogaster Frmd5 (28% identical), and 5 more. Paralogues in human: FRMD5 (51% identical), EPB41L3 (30% identical), EPB41L2 (29% identical), EPB41 (28% identical), EPB41L5 (28% identical), EPB41L1 (27% identical), EPB41L4B (26% identical), EPB41L4A (24% identical), FRMD6 (19% identical), MYLIP (17% identical).
Diseases named in the same sentence as FRMD3 in open-access papers:
FRMD3 is named in the same sentence as 23 diseases in open-access papers, as found by Europe PMC text mining. Sharing a sentence is not in itself a finding about the gene and the disease. The quoted sentences say what the papers report.
diabetic nephropathy (9 papers, 2011 to 2024). "One of the top-ranking genes from this subset, FRMD3, has previously been associated with the risk of developing diabetic kidney disease." (PMID 39450948, 2024). "To date, there is a limited number of studies on FRMD3, most of which reported the close association of FRMD3 gene polymorphisms with diabetic nephropathy." (PMID 36631457, 2023). "FRMD3 is presumed to be associated with susceptibility to diabetic nephropathy, and in recent years, several reports have reported its role in tumors." (PMID 35756646, 2022). "It appears that African Americans with diabetes and kidney disease who are not chromosome 22 nephropathy risk variant homozygotes are enriched for the presence of diabetic nephropathy and FRMD3 risk alleles." (PMID 21698141, 2011). "This genetic dissection ultimately allowed for detection of the FRMD3 diabetic nephropathy gene association in a subset of cases enriched for this disorder." (PMID 21698141, 2011). "Therefore, whether the regulation of FRMD3 on vimentin or focal adhesion could underlie the close association of FRMD3 gene variation and diabetic nephropathy could be worthy of further investigation." (PMID 36631457, 2023). "Because the link between the FRMD3 gene and diabetic nephropathy has recently been identified, very few studies are available focusing on mRNA and protein expression." (PMID 36945919, 2023). "However, genetic variants in another positional candidate gene, FERM domain containing 3 (FRMD3), have been recently reported to be associated with eGFR and diabetic nephropathy (DN)." (PMID 25885044, 2015). "Stratified analyses based on the chromosome 22 nephropathy risk haplotypes demonstrated that FRMD3 variants were associated with diabetic nephropathy risk in cases without two MYH9 (or APOL1) risk haplotypes." (PMID 21698141, 2011). "Although FERM-domain containing proteins interact with myosins, we do not feel that our genetic results support FRMD3 and MYH9 variants directly interacting to initiate diabetic nephropathy in African Americans." (PMID 21698141, 2011).
diabetes (6 papers, 2011 to 2023). "The first published study regarding variants in FRMD3 was a GWAS with T1DM patients from the GoKinD (Genetics of Kidneys in Diabetes) collection." (PMID 26719775, 2015). "Later the authors showed MYH9 polymorphisms specifically the E-1 haplotype to modulate the genetic effect of FERM domain-containing protein 3 (FRMD3) for diabetes susceptibility." (PMID 23285077, 2012). "Two other FRMD3 SNPs associated with DKD in the GoKinD collection (rs1888746 and rs13289150) were also associated with the development of severe nephropathy in the DCCT/EDIC (Diabetes Control and Complications Trial/Epidemiology of Diabetes Interventions and Complications) follow-up study." (PMID 26719775, 2015). "Diabetes induction increased serum levels of glucose, Cr, urea, MDA, and thiol, but decreased BMP7 and FRMD3 genes expression." (PMID 36945919, 2023). "FRMD3 protein expression reached borderline formal statistical significance when comparing patients with or without diabetes [0.66 (0.11–2.31) vs. 0.99 (0.07–2.87); P = 0.05]." (PMID 26753002, 2016). "Outside the context of diabetes, this study was not able to show an influence of rs1888747 SNP on FRMD3 gene and/or protein expression." (PMID 26753002, 2016).
Nephropathy (5 papers, 2011 to 2024). A nonspecific term referring to disease or damage of the kidneys. "The discrepant effect of FRMD3 protection in c22 nephropathy homozygotes, versus risk in non-c22 nephropathy homozygotes, raised the possibility that the T2DM-ESRD case group contained subsets of cases with different diseases." (PMID 21698141, 2011). "Examination of the top 100 SNP interactions with c22 risk variants identified SNPs within two previously reported nephropathy susceptibility genes, FRMD3 and SHROOM3." (PMID 21698141, 2011). "FRMD3 variants now appear to impact susceptibility to nephropathy from T1DM and T2DM with effects in European- and African-derived populations, apparently not in Japanese." (PMID 21698141, 2011). "It was also unclear whether FRMD3 was a susceptibility gene for only T1DM-associated nephropathy or contributed to other etiologies of kidney disease." (PMID 21698141, 2011). "Although the functional significance of the association of FRMD3 with DN is not clearly known, the promoter variant associated with DN may influence nephropathy through generating the necessary binding site for the proteins involved in the bone morphogenetic protein signaling pathways." (PMID 25885044, 2015). "We have identified a panel of kidney-specific transcripts correlated with severity and progression of kidney disease, and from this, we have identified a possible role for FRMD3 in tubule cell structure and health." (PMID 39450948, 2024). "Our analyses in 3263 AA T2DM-ESRD cases and non-diabetic, non-nephropathy controls revealed an approximate 25–30% increase in DN risk with multiple FRMD3 SNPs in subjects not homozygous for the MYH9 E1 risk haplotype (or APOL1 risk variants)." (PMID 21698141, 2011). "FRMD3 allele frequencies were compared between the 513 unrelated AAs with T2DM lacking nephropathy and the 1,592 T2DM-ESRD cases." (PMID 21698141, 2011). "We conclude that variants in FRMD3 contribute to the risk for nephropathy in AA with T2DM, an effect that was observed only after accounting for MYH9 (and less so APOL1) gene variants and evaluating a subset of AA cases likely enriched for T2DM-associated nephropathy." (PMID 21698141, 2011). "FERM domain containing 3 (FRMD3) is responsible for maintaining the shape and integrity of nephron cells, and bone morphogenetic protein 7 (BMP7) helps maintain function and reduce kidney damage." (PMID 36945919, 2023). "The FRMD3 SNPs that were associated with T1DM-associated nephropathy in GoKinD samples were subsequently tested in our AA T2DM-ESRD cases and non-diabetic, non-nephropathy controls." (PMID 21698141, 2011). "Markers in FRMD3, a gene associated with type 1 diabetic nephropathy in Caucasians, appeared to interact with MYH9; however, increased nephropathy risk was seen in diabetic cases lacking two MYH9 risk haplotypes, and protective effects were seen in those with two MYH9 risk haplotypes." (PMID 21698141, 2011). "In addition, FRMD3 allele frequencies in the 513 AA with T2DM lacking nephropathy were not significantly different compared to the 1,671 non-diabetic, non-nephropathy controls, whether or not stratified on MYH9 E1 haplotype homozygosity (all p-values>6E−1)." (PMID 21698141, 2011).
breast carcinoma (4 papers, 2022 to 2024). "However, the functional roles and the underlying mechanisms of FRMD3 in cancers including breast cancer remains largely unknown." (PMID 36631457, 2023). "Therefore, FRMD3 would act as a tumor suppressor in breast cancer, and its downregulation would be associated with poor clinical outcomes in breast cancer patients, indicating its potential as a prognostic marker and therapeutic target for breast cancer metastasis prevention and therapy." (PMID 36631457, 2023). "The current study revealed that hsa-miR-3651 is a predictor of LC in early breast cancer via its putative target protein FRMD3." (PMID 34865205, 2022). "Ubiquilin2 and myotubularin-1 recognize vimentin for degradation in skeletal muscle cells to avoid proteotoxic aggregate formation.In breast cancer, FERM domain-containing protein 3 (FRMD3) interacts with ubiquitin protein ligase E3A (UBE3A) to induce vimentin proteasomal degradation." (PMID 38383479, 2024). "Therefore, FRMD3 acted as a tumor suppressor to inhibit breast cancer cell proliferation, migration, and invasion both in vitro and in vivo." (PMID 36631457, 2023). "Thereafter, high FRMD3 expression was reported to be related to advanced clinicopathological features in rectal cancer patients, and FRMD3 was shown to be the target of Has-miR-3651, a novel predictor for breast cancer recurrence." (PMID 36631457, 2023). "In this study, we explored the downregulation of FRMD3 mRNA and its clinical relevance in breast cancer using the TCGA database and verified the lower levels of FRMD3 protein in both breast cancer cell lines and clinical tissue biopsy, as compared to normal controls." (PMID 36631457, 2023). "To obtain clues for further studies, we selected the functional genes that are positively correlated with FRMD3 (Pearson’s correlation coefficient ≥ 0.5) from breast cancer in the UALCAN database for GO enrichment and biological process cluster analysis in Metascape." (PMID 36631457, 2023). "Overall, these data indicate that FRMD3 may suppress proliferation, metastasis, and aggressiveness in breast cancer cells through modulating cell adhesion, cell cycles, and a series of pathways." (PMID 36631457, 2023). "Here, we proposed that FRMD3 could inhibit the adhesion and motility of breast cancer cells by inducing the ubiquitination and degradation of vimentin, an essential regulator of cancer metastasis." (PMID 36631457, 2023). "Another research reports the impact of FERM domain-containing protein 3 (FRMD3) on vimentin degradation, resulting in anti-proliferative and anti-metastatic roles in breast cancer." (PMID 38191501, 2024). "A comparison of the FRMD3 levels in different stages of BRCA displayed a stage-dependent tendency to decrease, indicating that FRMD3 expression decreased with the progression of breast cancer." (PMID 36631457, 2023). "In conclusion, our results suggest a mechanism by which FRMD3 interacts with vimentin and ubiquitin ligase UBE3A through its ubiquitin-like domain to promote proteasome degradation of vimentin, thereby exerting a unique function of FRMD3 in breast cancer progression." (PMID 36631457, 2023). "In this study, we demonstrated that FRMD3, which is significantly downregulated in breast cancer, binds with vimentin through its ubiquitin-like domain, leading to the ubiquitination-mediated degradation of vimentin via recruiting ubiquitin ligase UBE3A in breast cancer cells." (PMID 36631457, 2023).
lung carcinoma (3 papers, 2012 to 2023). "As early as 2007, FRMD3 was identified as a tumor suppressor gene in lung cancer, suggesting a potential role in the origin and progression of lung cancer." (PMID 36631457, 2023). "FRMD3 (FERM domain containing 3) is over-expressed in normal human lung tissue compared with tissue from lung tumors of lung carcinoma patients suggesting its important role in the origin and progression of lung cancer." (PMID 22952805, 2012). "FRMD3 was also found to be a candidate TSG in lung cancer and acute myeloid leukemia." (PMID 35887658, 2022).
non-small cell lung carcinoma (3 papers, 2021 to 2024). A group of at least three distinct histological types of lung cancer, including non-small cell squamous cell carcinoma, adenocarcinoma, and large cell carcinoma. "High expression of FRMD3 is associated with good prognosis in non-small cell lung carcinoma but poor prognosis in rectal cancer, suggesting a tissue-specific role for this gene." (PMID 38398114, 2024). "FRMD3 is a tumour-suppressor in non-small cell lung carcinoma as it induces apoptosis." (PMID 38398114, 2024). "The FRMD3 gene was identified as a novel putative tumor suppressor in non-small cell lung cancer." (PMID 35756646, 2022). "The current research mechanism of FRMD3 in COAD has not been reported to date, but it has been reported that non-small cell lung carcinoma (NSCLC) is highly correlated with reduced FRMD3 expression, which could induce apoptosis by regulating the activity of caspases in NSCLC." (PMID 34322151, 2021).
rectal cancer (3 papers, 2016 to 2023). A primary or metastatic malignant neoplasm that affects the rectum. "A previous study of FRMD3 mentioned that high levels of FRMD3 in rectal cancer lead to a poor disease survival rate." (PMID 35887658, 2022).
type 2 diabetes (3 papers, 2011 to 2013). "Three of these loci, located on chromosome 9q21.32 near the FRMD3 gene, chromosome 11p15.4 at the CARS gene, and chromosome 13q33.3 at the MYO16/IRS2 locus, have since been confirmed in multiple diverse collections of unrelated T1D or type 2 diabetic (T2D) patients." (PMID 23555951, 2013).
Hypertension (2 papers, 2016 to 2017). The presence of chronic increased pressure in the systemic arterial system. "FRMD3 protein expression did not correlate with age (r2 = −0.13; P = 0.364) and was similar in females and males [0.73 (0.11–2.87) vs. 0.79 (0.07–2.64); P = 0.959] and in patients with or without arterial hypertension [0.73 (0.07–2.31) vs. 1.05 (0.11–2.87); P = 0.212]." (PMID 26753002, 2016).
prostate carcinoma (2 papers, 2022 to 2024). A carcinoma that arises from epithelial cells of the prostate gland. "In prostate cancer, miR-423-5p is involved in cancer progression, and enhances migratory and invasive abilities via FRMD3, a tumor suppressor gene." (PMID 39677943, 2024).
benign neoplasms of the brain (1 paper, 2022). "Four signals associated with LRP1B (rs7599907), FRMD3 (rs10121898), MC4R (rs8087522), and ETS1 (rs76404385) identified benign neoplasms of the brain." (PMID 35887658, 2022). "Despite limited specific clinical research between FRMD3 and brain neoplasms, FERMD might be relevant as a TSG in benign neoplasms of the brain, as indicated by our TPMI results in the Han population." (PMID 35887658, 2022).
colon cancer (1 paper, 2022). "In contrast, reports on rectal and colon cancer revealed that up-regulation of FRMD3 was associated with worse response to chemoradiotherapy." (PMID 34865205, 2022).
eczema herpeticum (1 paper, 2024). "A whole-genome sequencing study revealed that FRMD3 is associated with eczema herpeticum." (PMID 39064094, 2024).
keloid (1 paper, 2024). An irregularly shaped, elevated mark on the skin caused by deposits of excessive amounts of collagen during wound healing. "Another study showed that FRMD3 is related to the risk of keloid formation." (PMID 39064094, 2024).
medulloblastoma (1 paper, 2022). A malignant, invasive embryonal neoplasm arising from the cerebellum. "Both LRP1B and FRMD3 serve as TSGs in brain tumors, and some research has shown that LRP1B deletion affects the prognosis of malignant brain neoplasms, including GBM and medulloblastoma, in the U.S. population according to TCGA data." (PMID 35887658, 2022).
neoplasms of the brain (1 paper, 2022). "Although there is little research on FRMD3 in neoplasms of the brain, FRMD6 inhibits activation of tyrosine kinase receptors to overcome tumor growth and disease progression in GBM." (PMID 35887658, 2022). "Other SNP profiles revealed different molecules, including DDP6, NDUFB9, EDARADD, EST1, MC4R, LRP1B, and FRMD3, which perform different roles in brain neoplasms or malignancies." (PMID 35887658, 2022).
type 1 diabetes (1 paper, 2025). "Recent studies in type 1 diabetes (T1D) cohorts have highlighted robust loci such as protective variants in COL4A3 (e.g., rs55703767), as well as signals in AFF3, FRMD3, and the RGMA–MCTP2 region, which are consistently associated with albuminuria, eGFR decline, and ESKD." (PMID 41585789, 2025).